CD24 (CD24 molecule)
Diseases named in the same sentence as CD24 in open-access papers (continued):
Sharing a sentence is not in itself a finding about the gene and the disease.
mesothelioma (6 papers, 2009 to 2024). A usually malignant and aggressive neoplasm of the mesothelium which is often associated with exposure to asbestos. "CD24 was highly expressed in human mesothelioma tissues (28/45 cases, 62%) and associated with the loss of NF2 and p16." (PMID 33298865, 2020). "The results showed that CD24 significantly increased the risk of tumorigenesis and the progression of BRCA, mesothelioma (MESO), and skin cutaneous melanoma (SKCM)." (PMID 39791710, 2024). "To further validate CD24 expression in MPM patients, we analyzed a public cohort of 86 patients from The Cancer Genome Atlas Mesothelioma." (PMID 33298865, 2020). "Other genes including CD24, CD117, uPAR, and CD133 that were reported previously in mesothelioma were upregulated as well." (PMID 29699510, 2018). "Moreover, we previously identified CD9, along with side population, CD24 and CD26 cells, as a cancer stem cell marker of mesothelioma, thus demonstrating its potential for cancer stem cell-targeted therapy in the future." (PMID 23128478, 2013). "Moreover, we previously identified CD9 along with side population CD24 and CD26 cells to be markers of cancer stem cells in mesothelioma." (PMID 23128478, 2013).
pancreatic ductal adenocarcinoma (6 papers, 2016 to 2021). An infiltrating adenocarcinoma that arises from the epithelial cells of the pancreas. "Co-expressing populations of CD24+/CD44+/EpCAM+/CD133+ with pro-tumorigenic gene expression profile were reported in pancreatic ductal adenocarcinoma." (PMID 30121075, 2018). "This has been observed in pancreatic intraepithelial neoplasias (PanIN) whereby CD90 and CD24 co-expression may specifically enable early detection of PanIN before it developed into pancreatic ductal adenocarcinoma (PDAC)." (PMID 34572431, 2021). "Meanwhile, IFN up-regulated the expression of the CSC markers CD24, CD44, and CD133 and promoted the migration and invasion of pancreatic ductal adenocarcinoma cells." (PMID 34572431, 2021). "Surface CD24 has previously been described, together with CD44 and ESA, for the characterization of putative cancer stem cells in pancreatic ductal adenocarcinoma (PDAC), the most fatal of all solid tumors." (PMID 27203385, 2016).
sarcoidosis (6 papers, 2020 to 2025). Sarcoidosis is a multisystemic disorder of unknown cause characterized by the formation of immune granulomas in involved organs. "In the meantime, it was found that the proportion of Bregs (CD19+CD24+CD38+) in the peripheral blood of patients with active sarcoidosis was significantly higher when compared to patients with stable sarcoidosis and healthy controls." (PMID 32508842, 2020). "Foremost, in peripheral blood samples from sarcoidosis patients we observed higher frequencies of CD24+++ CD38+++ B cells compared with those in matched HC." (PMID 31974463, 2020). "Moreover, we found that in sarcoidosis patients there are increased levels of B cell subsets, which were previously shown to display regulatory capacities (CD24+++ CD38+++ and CD5 + CD27−)." (PMID 31974463, 2020).
squamous cell carcinoma (6 papers, 2003 to 2023). A carcinoma arising from squamous epithelial cells. "Orthotopically transplanted syngeneic squamous carcinoma model in the tongue of CD24−/− and CD24+/− mice confirmed the protective roles of CD24 against cancer." (PMID 38138858, 2023). "CD24 immunopositivity was noted in 43.93% (29/69) of well-differentiated squamous cell carcinoma (WDSCC) and 44.89% (22/49) of moderately differentiated squamous cell carcinoma (MDSCC) + PDSCC." (PMID 37664387, 2023). "CD24 expression was observed more frequently in adenocarcinomas (AC) than in squamous cell carcinomas (SCC)." (PMID 26578846, 2015). "As above, CD24 expression was observed more frequently in adenocarcinomas (AC) than in squamous cell carcinomas (SCC)." (PMID 26578846, 2015). "Further histological analysis of tissue sections stained with hematoxylin and eosin (H&E) confirmed the presence of nasopharyngeal squamous cell carcinoma and well-differentiated keratinizing squamous carcinoma at the site where CD24+ cells were initially injected." (PMID 24955581, 2014).
cholangiocarcinoma (5 papers, 2013 to 2024). A carcinoma that arises from the intrahepatic biliary tree (intrahepatic cholangiocarcinoma) or from the junction, or adjacent to the junction, of the right and left hepatic ducts (hilar cholangiocarcinoma). "CD24 is a cell adhesion molecule that was shown to be associated with chemo-resistance capabilities and poor survival in cholangiocarcinoma." (PMID 26207380, 2015). "In the present study, the underlying mechanism of aggressive CD24+ cholangiocarcinoma cell behavior was elucidated." (PMID 24179538, 2013). "The present study indicates that CXCR4 and ERK1/2 are induced by CD24 and that these proteins are associated with cholangiocarcinoma cell invasion." (PMID 24179538, 2013). "The aim of the present study was to assess the signal transduction potential of CD24 by identifying the putative signaling molecules associated with CD24 in cholangiocarcinoma." (PMID 24179538, 2013). "CD24 expression has been linked to the aggressiveness of cholangiocarcinoma cells and the adverse prognosis of cholangiocarcinoma patients." (PMID 24179538, 2013). "However, the underlying mechanisms of the CD24 induction of cholangiocarcinoma cell migration and invasion have yet to be investigated." (PMID 24179538, 2013). "In conclusion, the results of the present study showed that CD24 has a major role in cholangiocarcinoma cell invasion." (PMID 24179538, 2013). "Therefore, the purpose of the present study was to investigate the roles of CD24 in the migration and invasion of cholangiocarcinoma and to identify the targets induced by CD24 in cholangiocarcinoma cells." (PMID 24179538, 2013). "We previously investigated the expression of CD24 in cholangiocarcinoma specimens and its prognostic significance, and our results demonstrated that high CD24 expression was significantly correlated with lymph node metastasis and positive surgical margins in cholangiocarcinoma patients." (PMID 24179538, 2013). "Additional studies are required to determine whether these molecules affect the aggressiveness of CD24+ cholangiocarcinoma cells." (PMID 24179538, 2013). "Furthermore, it was proposed that CD24 may have a role as a new target for directed molecular therapy in cholangiocarcinoma, as decreased tumor cell invasiveness was observed with inhibition of CD24." (PMID 26207380, 2015). "For in vitro studies, we isolated CD24+ and CD24− cell populations from RMCCA1 cholangiocarcinoma cells using the magnetic-activated cell sorting (MACS) system." (PMID 24179538, 2013). "The magnetic-activated cell sorting system was used to isolate CD24+ and CD24− cell populations from RMCCA1 cholangiocarcinoma cells." (PMID 24179538, 2013). "Additionally, a cell‐type‐dependent correlation of CD24 to the chemokine receptor CD184 (CXCR4) was found; for example, in pre‐B lymphocytes, CD24 negatively regulated CD184, while in cholangiocarcinomas, CD24 induced CD184 expression." (PMID 34293822, 2022). "The present study demonstrated that blocking CXCR4 signaling with AMD3100 results in decreased motility and invasion ability in CD24+ and CD24− cells (although to a greater extent in CD24+ cells), indicating that CXCR4 is important in cholangiocarcinoma cell invasiveness." (PMID 24179538, 2013).
colorectal adenocarcinoma (5 papers, 2014 to 2024). The most common type of colorectal carcinoma. "They performed dual-luciferase reporter assays in HT29 colorectal adenocarcinoma cells with a reporter construct harboring the 3′-UTR of the CD24 gene." (PMID 38674063, 2024). "Some studies suggest that loss of CD24 expression is associated with poorer outcomes, while others suggest that CD24 is a good prognosis marker in CRC, being down-regulated in stage IV colorectal adenocarcinoma." (PMID 39061234, 2024). "CD24 has been shown to be related to invasiveness and differentiation of colorectal adenocarcinoma." (PMID 24612587, 2014). "A study demonstrated that the human colorectal adenocarcinoma cell line HT-29 and Hct116 cells can be CD24-positive and CD24-negative controls for CRC, respectively." (PMID 31614769, 2019).
experimental autoimmune encephalomyelitis (5 papers, 2009 to 2023). An autoimmune demyelinating disease of the central nervous system that is produced experimentally in animals by the injection of homogenized brain or spinal cord in Freund's adjuvant. "For example, while CD24 polymorphisms have been studied in experimental autoimmune encephalomyelitis (EAE) and various cancer types, their examination within the scope of neural cancers has been lacking." (PMID 38313430, 2023). "In the experimental model for MS, experimental autoimmune encephalomyelitis (EAE), CD24 is essential for autoreactive T cells as well as resident CNS lymphocytes." (PMID 38313430, 2023).
inflammatory bowel disease (5 papers, 2017 to 2021). A spectrum of small and large bowel inflammatory diseases of unknown etiology. "Furthermore, in a recent study using CD24 knockout mice, we observed that CD24 is an essential player in inflammatory bowel disease pathogenesis." (PMID 33562144, 2021).
metabolic syndrome (5 papers, 2021 to 2023). A cluster of metabolic risk factors for CARDIOVASCULAR DISEASES and TYPE 2 DIABETES MELLITUS. "The recognition of CD24 by Siglec-E through sialoside-based interactions negatively regulates metaflammation and offers protection against metabolic syndrome." (PMID 38313430, 2023). "Siglec-E’s sialylation-dependent recognition of CD24 results in the recruitment of SHP-1 and the suppression of metaflammation, therefore preventing metabolic syndrome." (PMID 37846296, 2023). "In addition, we have previously associated the C248T SNP with statistically significant higher blood levels of total cholesterol and LDL-C (unpublished data), suggesting that CD24 may also play a role in dyslipidemia, possibly through regulation of PPARγ expression." (PMID 33467499, 2021).
prostate tumors (5 papers, 2012 to 2021). "Prior to the discovery of CD24 as a “don’t eat me” signal, docetaxel-loaded PLGA-PEG NPs conjugated with anti-CD24 were found to have a 10-fold higher prostate tumor accumulation in mice and showed potential for CD24-tagged NPs as an imaging agent." (PMID 33748077, 2021). "CD24 transcripts are also significantly increased in human prostate tumors relative to benign prostate hyperplasias." (PMID 26978528, 2016). "Furthermore, while our study was in preparation, others reported that CD24 deficiency in TRAMP mice results in delayed onset of prostate tumorigenesis, but that all mice had developed prostate tumors by 5 months of age." (PMID 26978528, 2016). "Together, our data suggest that while CD24 is distinctively expressed during the early development of murine mammary and prostate tumors, it is not essential for the formation of tumors developing in MMTV-PyMT, Apc1572T/+ and TRAMP mice." (PMID 26978528, 2016). "At first sight, reduced CD24 expression in later stages of MMTV-PyMT and Apc1572T/+ tumors, and absence of CD24 expression in a proportion of advanced TRAMP prostate tumors may appear contradictory with this notion." (PMID 26978528, 2016).
renal cell carcinoma (5 papers, 2003 to 2023). "It was also determined that PROM1 and CD24 co-expression was limited in renal cell carcinoma (RCC) cell lines." (PMID 37108999, 2023). "Galleggiante and his colleagues found that the CD133+/CD24+ tumor cells isolated from human renal cell carcinoma tissues possessed the CSCs characteristics such as self-renewal ability and multi-differentiation potential." (PMID 28279221, 2017). "It has been revealed that CD133, CD24, CD105, Snail, Nanog, Twist, OCT-3/4, CRT2, BCL-2,MDR1, KLF4 and so on are stemness markers in CSCs of renal cell carcinoma or other types of tumor." (PMID 28279221, 2017). "The CSCs have been isolated and identified in human renal cell carcinoma from solid tumor tissues and established cell lines, using Magnetic-activated cell sorting (MACS) or flow cytometry system based on CD133, CD24, CD105, ALDH1, Hoechst 33,342 and so on." (PMID 28279221, 2017).
retinoblastoma (5 papers, 2012 to 2025). A malignant tumor that originates in the nuclear layer of the retina. "In retinoblastoma (RB), CD24 recruits lipid rafts and activates the PTEN/AKT/mTORC1 signaling pathway." (PMID 40486886, 2025). "CD24 knockdown was further demonstrated to markedly decrease autophagic flux, inhibit the formation of autophagosomes and increase the sensitivity of retinoblastoma cells to vincristine therapy." (PMID 35884937, 2022). "The present study thus shows an obvious correlation between CD24 immuno expression with increasing histological grade of retinoblastoma." (PMID 27022367, 2016). "Present study was designed to evaluate the differential expression of CD24 in different histological grades of retinoblastoma and to assess the prognostic importance of CD24 expression by correlation with TNM staging and histological grading." (PMID 27022367, 2016). "CD24 immuno reactivity according to different histopathological grades of retinoblastoma (n = 68)." (PMID 27022367, 2016). "CD24 immuno staining according to TNM staging of retinoblastoma (n=68)." (PMID 27022367, 2016). "A total 68 diagnosed cases of retinoblastoma were selected for CD24 immuno staining." (PMID 27022367, 2016). "Correlation of CD24 expression with histological grading and TNM staging of retinoblastoma." (PMID 27022367, 2016). "This study also emphasizes that majority of well differentiated retinoblastoma were in lower TNM stage i-e stage I and II and a vast majority showed negative staining for CD24." (PMID 27022367, 2016).
Stroke (5 papers, 2022 to 2025). Sudden impairment of blood flow to a part of the brain due to occlusion or rupture of an artery to the brain. "SPRC (ZYZ-802), by modulating CBS, reduces astrogliosis, Aβ deposition, and inflammation in Alzheimer’s disease via NF-κB/MAPK, inhibiting TNF-α, COX-2, and ERK1/2, and enhancing microglial migration through CD24 and Src/Fak/Pyk2, effects comparable to those in stroke and neuroinflammation." (PMID 41465271, 2025). "Therefore, the mechanism could be owing to the regulation of CBS by SPRC with the promoted expression of H2S in brain tissue, and H2S further stimulated the expression of CD24 and ultimately alleviated stroke diseases." (PMID 39953809, 2025). "However, our findings align with this complexity, demonstrating that certain phenotypes associated with B cell activity, such as CD19 on CD24+ CD27+, CD20 on IgD- CD27-, CD25 on naive-mature B cell, CD27 on IgD- CD38br, IgD+CD38dim %B cell are linked to an increased risk of stroke." (PMID 38894965, 2024).
thyroid cancer (5 papers, 2016 to 2025). "Also ALDH1A1 positivity rates in normal/cancerous thyroid tissues/cells and expression levels of CD133, SSEA-1, and CD24 in thyroid cancer cells varied among different studies." (PMID 26973599, 2016). "Whether there is a relationship between CD24 and the development, recurrence, and non-uptake of iodine in thyroid cancer needs to be explored in further experiments." (PMID 37907864, 2023).
asthma (4 papers, 2009 to 2025). "In our libraries, the expression of CD24 was found to be down-regulated 12 times in asthma while up-regulated 7 times by acupuncture." (PMID 19419550, 2009). "However, it has been reported that people with asthma have decreased percentages of CD24+CD27+ B cells, which are required for the induction of IL10+ T cells." (PMID 29881878, 2018). "We found that ICTs (CD24 on IgD+ CD38br and CD3 on CD28+ CD4+) influence asthma through two pathways, mediated by PMs (S‐methylcysteine sulfoxide levels and 1‐myristoyl‐2‐arachidonoyl‐GPC [14:0/20:4] levels)." (PMID 40551049, 2025).
brain cancer (4 papers, 2014 to 2026). A primary or metastatic malignant neoplasm affecting the brain. "CD24, a cell adhesion glycosylphosphatidylinositol anchor protein, has been reported to be expressed in lung, breast, ovarian and brain cancers, but its expression in medulloblastoma has only recently begun to be investigated." (PMID 30657775, 2019). "For example, blockade of Notch-I signaling pathway has been demonstrated to reduce the fraction of CD44+CD24 subpopulation and also decreased the instance of brain metastasis of brain cancer." (PMID 28785557, 2017).
depression (4 papers, 2021 to 2025). "More recently, regulatory B cell populations, such as IgD–CD27+ naïve B cells, CD1d–CD5+ B cells, and CD24–CD38hi transitional B cells, are reported to be diminished in individuals with severe depression." (PMID 41356500, 2025). "Our study aims to characterize the anxiety-like behavior, depression-like behavior, and cognitive performance of CD24 knockout mice compared with CD24 wild-type (WT) mice." (PMID 33562144, 2021). "WT and CD24−/− mice were assessed at the age of 2, 4, and 6 months for depression-like behavior in the FST and TST test." (PMID 33562144, 2021). "In our study, the expression level of CD24 was also found to be increased in blood samples of patients with depression, suggesting that CD24 may be potentially related to emotional regulation." (PMID 37547246, 2023).
diabetes (4 papers, 2018 to 2023). "Furthermore, they concluded the association between the CD24 and insulin sensitivity, suggesting its possible mechanism for diabetes." (PMID 36900128, 2023). "Furthermore, the association between the CD24 and insulin sensitivity suggests a possible mechanism for diabetes as a cancer risk factor." (PMID 33467499, 2021). "This latter phenotype is indicative of regulatory B cells, but does not match the profiles we identified in areas 2 and 6 of the SPADE tree, where reduced expression of CD24 was apparent in newly diagnosed individuals and those with long-standing diabetes." (PMID 29881878, 2018). "Instead, we found that CD95 expression was reduced on switched CD27+IgD− memory B cells in individuals with long-standing diabetes, consistent with the findings of a recent study by Hanley and colleagues, who also reported lower frequencies of CD24++CD38++ B cells in people with type 1 diabetes." (PMID 29881878, 2018). "Furthermore, in individuals with newly diagnosed diabetes, CD24 expression was reduced on unswitched CD27intIgD+ memory B cells (area 6: p < 0.01 in Study A, p < 0.05 in Study B)." (PMID 29881878, 2018). "Statistical analysis of area 2, which comprised switched memory B cells with a CD21+CD24+CD27+CD38intCD95+IgD− phenotype, revealed that CXCR3 expression was reduced in individuals with long-standing diabetes relative to healthy donors in Study A (p < 0.05) and Study B (p < 0.005)." (PMID 29881878, 2018). "However, the involvement of CD24 in diabetes is not entirely clear." (PMID 33467499, 2021).
embryonal carcinoma (4 papers, 2018 to 2024). A non-seminomatous malignant germ cell tumor characterized by the presence of large germ cells with abundant cytoplasm resembling epithelial cells, geographic necrosis, high mitotic activity, and pseudoglandular and pseudopapillary structures formation. "CD24 is a membrane protein that has also been proposed as a target for NK-CAR immunotherapy by virtue of its SOX2-mediated transactivation in embryonal carcinoma cells enabling the induction of cell death in CD24-positive cells in vitro." (PMID 38275869, 2024). "This study presents the (epi)genetic mechanisms regulating the expression of the signaling transducer CD24 in embryonal carcinoma (EC), a germ cell tumor subtype with embryonic stem cell‐like features." (PMID 34293822, 2022).